MALT1 (MALT1 paracaspase)
Description:
Protease that enhances BCL10-induced activation: acts via formation of CBM complexes that channel adaptive and innate immune signaling downstream of CARD domain-containing proteins (CARD9, CARD11 and CARD14) to activate NF-kappa-B and MAP kinase p38 pathways which stimulate expression of genes encoding pro-inflammatory cytokines and chemokines. Mediates BCL10 cleavage: MALT1-dependent BCL10 cleavage plays an important role in T-cell antigen receptor-induced integrin adhesion. Involved in the induction of T helper 17 cells (Th17) differentiation. Cleaves RC3H1 and ZC3H12A in response to T-cell receptor (TCR) stimulation which releases their cooperatively repressed targets to promote Th17 cell differentiation (By similarity). Also mediates cleavage of N4BP1 in T-cells following TCR-mediated activation, leading to N4BP1 inactivation. May also have ubiquitin ligase activity: binds to TRAF6, inducing TRAF6 oligomerization and activation of its ligase activity.
Synonyms: MLT; PCASP1; IMD12; MLT1
Tractability: Small molecule: an approved drug acts on it; a structure with a bound ligand is known; a high-quality ligand is known. PROTAC: ubiquitination databases record sites on it; its protein half-life has been measured; a small molecule that binds it is known.
Target class: Enzyme; Hydrolase
Chemical probes: MLT-748 (high quality), NVS-MALT1 (high quality), SCM-02-138 (high quality)
Safety:
Unwanted effects reported when the protein is acted on. In parentheses: how it was acted on, where the effect was seen, and who reports it.
Severe reduction in regulatory T cells (inhibition; immune; source: Brennan et al. (2024))
signs of immune dysregulation, polyendocrinopathy, enteropathy, X-linked (IPEX)-like pathology (inhibition; immune; source: Brennan et al. (2024))
Gene: Protein-coding gene on chromosome 18 (58,671,426 to 58,754,477, forward strand). Ensembl gene ENSG00000172175.
Subcellular location: Cytoplasm, perinuclear region; Nucleus
Subcellular location (Human Protein Atlas): Nucleoli fibrillar center; Cytosol
Pathways (Reactome):
Immune System: Activation of NF-kappaB in B cells; CLEC7A (Dectin-1) signaling; CLEC7A/inflammasome pathway; Downstream TCR signaling; FCERI mediated NF-kB activation
Gene Ontology:
Molecular function: endopeptidase activator activity; endopeptidase activity; identical protein binding; kinase activator activity; peptidase activity; protein binding; small molecule binding; ubiquitin-protein transferase activity; cysteine-type endopeptidase activity; protease binding
Biological process: nuclear export; positive regulation of canonical NF-kappaB signal transduction; positive regulation of interleukin-1 beta production; positive regulation of interleukin-2 production; positive regulation of T cell cytokine production; protein catabolic process; proteolysis; regulation of apoptotic process; T cell receptor signaling pathway; B cell activation; defense response; innate immune response; negative regulation of apoptotic process; positive regulation of protein ubiquitination; positive regulation of T-helper 17 cell differentiation; regulation of canonical NF-kappaB signal transduction; cellular response to lipopolysaccharide; lipopolysaccharide-mediated signaling pathway; positive regulation of adaptive immune response based on somatic recombination of immune receptors built from immunoglobulin superfamily domains; positive regulation of immune effector process; positive regulation of multicellular organismal process
Cellular component: CBM complex; cytoplasm; nucleus; protein-containing complex; cytosol; perinuclear region of cytoplasm; polkadots
Genetic constraint (gnomAD): Loss-of-function variants: 16 observed, 41.86 expected, observed/expected ratio (o/e) 0.38, 90% interval 0.26 to 0.58. The upper end of that interval is the gene's LOEUF score, 0.58, which puts it in group 2 of 6, group 1 being the genes least tolerant of losing a copy. Missense variants: 529 observed, 695.83 expected, observed/expected ratio (o/e) 0.76, 90% interval 0.71 to 0.82. Synonymous variants: 274 observed, 264.74 expected, observed/expected ratio (o/e) 1.03, 90% interval 0.94 to 1.14.
Gene-disease validity (ClinGen):
ClinGen rates the evidence that MALT1 causes each of these diseases.
combined immunodeficiency due to MALT1 deficiency (autosomal recessive): Definitive.
Homologues: Orthologues: chimpanzee MALT1 (99% identical), macaque MALT1 (99% identical), dog MALT1 (92% identical), pig MALT1 (91% identical), rat Malt1 (88% identical), mouse Malt1 (88% identical), rabbit MALT1 (86% identical), guinea pig MALT1 (84% identical), tropical clawed frog malt1 (58% identical), zebrafish malt1 (50% identical), Caenorhabditis elegans malt-1 (20% identical).
Diseases named in the same sentence as MALT1 in open-access papers:
MALT1 is named in the same sentence as 157 diseases in open-access papers, as found by Europe PMC text mining. Sharing a sentence is not in itself a finding about the gene and the disease. The quoted sentences say what the papers report.
MALT lymphoma (78 papers, 2006 to 2025). An indolent, extranodal type of non-Hodgkin lymphoma composed of small B-lymphocytes (centrocyte-like cells). "Dysregulated MALT1 activity is linked to lymphoid malignancies (e.g., MALT lymphoma), autoimmune diseases, and immunodeficiencies." (PMID 40338274, 2025). "For 17 localized pSS-associated MALT lymphomas, we analyzed the presence of nonsynonymous mutations, copy number alterations (CNAs) and MALT1 translocations." (PMID 35205758, 2022). "We previously showed that pulmonary mucosa-associated lymphoid tissue (MALT) lymphoma can be diagnosed by detecting MALT lymphoma translocation gene 1 (MALT1) translocations in bronchoalveolar lavage fluid (BALF) cells." (PMID 34873224, 2021). "Owing to its 100% specificity, the FISH-based detection of MALT1 rearrangements in BALF cells would significantly improve the diagnostic accuracy for MALT lymphomas." (PMID 34873224, 2021). "Chromosomal translocations associated with MALT lymphoma include API2/MALT1, IGH/MALT1, BCL10/IGH, and trisomy 3 and 1814,23,27." (PMID 34873224, 2021). "Mucosa-associated lymphoid tissue lymphoma translocation protein 1 (MALT1) was coined based on the discovery of its translocated gene product in patients with MALT lymphoma." (PMID 32425939, 2020). "Chromosomal translocation of MALT1 associated with MALT lymphoma is often restricted to the endometrium." (PMID 31053132, 2019). "The genetic hallmark of MALT lymphoma is a translocation of MALT1 gene." (PMID 38440231, 2024). "Finally, these NF-κB pathway mutations and MALT1 translocations appeared to be enriched in gastric MALT lymphoma unresponsive to H. pylori eradication and were largely mutually exclusive, albeit based on a small series of cases." (PMID 34203889, 2021). "Therapeutic targeting of MALT1 protease activity might therefore become a promising approach for the treatment of MALT lymphomas and other B cell lymphomas associated with deregulated NF-κB signaling." (PMID 25922601, 2015). "In primary hepatic MALT lymphoma, the most frequent translocation is t (q32; q21), which brings the mucosa-associated lymphoid tissue 1 (MALT1) gene to the downstream of the IgG enhancer and makes MALT1 overexpressed, thus resulting in activation of the NF-κB pathway." (PMID 36110965, 2022). "Mucosa-associated lymphoid tissue lymphoma translocation protein 1 (MALT1) was initially identified in MALT lymphomas, from which its name is derived." (PMID 41567547, 2025). "Further case studies are needed to elucidate the frequency of MALT1 abnormalities in pleural MALT lymphoma." (PMID 41170225, 2025). "Murine Sca1+Lin− immature cells with human MALT1 expression had early priming toward B-cell differentiation and initiated clonal hematopoiesis that later progressed to MALT lymphoma." (PMID 38440231, 2024). "This study investigated the long-term outcomes of patients with gastric MALT lymphoma based on the presence of chromosomal aberrations and revealed that progression or recurrence occurs more frequently in patients with extra copies of MALT1 (Group C)." (PMID 38418651, 2024). "This is the most common chromosomal translocation in MALT lymphomas and has disrupted the function of the MALT1 gene." (PMID 37274282, 2023). "The oncogenic potential of MALT1 has been demonstrated in a mouse model that allows specific MALT1 expression in hematopoietic stem/progenitor cells which results in the development of MALT lymphoma." (PMID 35203553, 2022). "MALT1 overexpression has been reported mainly in MALT lymphoma, but it can also be observed in other malignancies, such as B-cell acute lymphoblastic leukemia (B-ALL) and diffuse large B-cell lymphoma (DLBCL)." (PMID 35203553, 2022). "The probe for MALT1 translocation used in the present study detected both API2/MALT1 and IGH/MALT1 translocations, and the MALT1 translocation rate in patients with pulmonary MALT lymphomas observed here (28.6%) was consistent with previous reports." (PMID 34873224, 2021).
MALT lymphoma (continued). "Analysis of MALT1 translocation frequencies in each group indicated that 28.6% (2/7) patients with MALT lymphoma were positive, whereas all other patients, including those with non-MALT B-cell lymphoma, were negative for MALT1 translocation." (PMID 34873224, 2021). "The API2/MALT1 translocation was detected in 30–70% of MALT lymphoma lung tissues obtained by SLB20,21,27–29, whereas the IGH/MALT1 translocation was observed in 6–10% of patients with MALT lymphoma." (PMID 34873224, 2021). "The rate of MALT1 translocations among patients with MALT lymphoma was significantly higher than that in the other group (p < 0.05)." (PMID 34873224, 2021). "A tumor-promoting role of MALT1 has been found in a subset of diffuse large B cell lymphoma (DLBCL) and MALT lymphoma, indicating MALT1 as an attractive anticancer drug target." (PMID 34926571, 2021). "The sensitivity and specificity of MALT1 translocations for diagnosing MALT lymphoma were 28.6% and 100%, respectively." (PMID 34873224, 2021). "The cIAP2-MALT1 chimeric protein lacks E3 activity, and it leads to a decrease in ubiquitinylation and cleavage of cIAP2 and MALT1 target Bcl10 in MALT lymphomas." (PMID 33825941, 2021). "Up to 50% of MALT lymphomas carry a chromosomal translocation resulting in the production of a chimeric protein (BIRC3-MALT1) and in transcriptional deregulation of BCL10, MALT1, and FOXP1, with variable frequencies depending on the site of occurrence." (PMID 33499258, 2021). "The sensitivity and specificity of MALT1 translocation testing for MALT lymphoma diagnosis were 28.6% and 100%, respectively." (PMID 34873224, 2021). "Detection of light chain restriction by IHC, flow cytometry, and/or clonality by molecular analysis as well as of MALT1 gene rearrangements by FISH or flow cytometry further support a diagnosis of MALT lymphoma over a reactive inflammatory process." (PMID 33499258, 2021). "The sensitivity and specificity of MALT1 translocation detection for MALT lymphoma diagnosis were 28.6% and 100%, respectively." (PMID 34873224, 2021). "The human MALT1 gene was initially discovered through the study of chromosomal translocation in MALT lymphomas." (PMID 33072583, 2020). "The MALT1 gene was originally identified as the target of recurrent translocations in MALT lymphomas." (PMID 30214442, 2018). "Chromosomal translocations involving the genes BCL10 or MALT1, which are frequent in other types of MALT lymphomas, are rare in OAML." (PMID 27566587, 2016). "Here we investigate the mechanism by which the c-IAP2/MALT1 fusion protein contributes to the development of MALT lymphoma." (PMID 21048983, 2010). "In H. pylori-positive gastric MALT lymphomas unresponsive to eradication therapy, NF-κB pathway mutations, including TNF-receptor-associated factor 3 (TRAF3) mutations and TNF-alpha-induced protein 3 (TNFAIP3) mutations, and MALT1 translocations are enriched." (PMID 35053607, 2022). "Interestingly, one of these genes, namely MALT-1, is a crucial regulator of NF-κB pathway in MALT lymphoma and appears to be involved in the regulation of NF-κB activation in HTLV-1 mediated leukemogenesis." (PMID 35979358, 2022). "The most common structural chromosomal abnormality in MALT lymphoma is the generation of the API2-MALT1 fusion transcript and chimeric protein, which comprises the N-terminal API2(cIAP2) region with three intact BIR domains and the C-terminal MALT1 region containing an intact caspase-like domain." (PMID 33825941, 2021). "These two studies suggest that, like in a subset of MALT lymphomas, MALT1 overexpression per se may play a role in promoting carcinogenesis, potentially by spontaneous aggregation-mediated activation of MALT1." (PMID 30214442, 2018). "Another type of lymphoma with constitutive MALT1 activity is the MALT lymphoma." (PMID 26507244, 2016).
MALT lymphoma (continued). "However, the frequency of API2/MALT1 fusion gene varies among MALT lymphomas originating from different anatomical sites, and little is known about the small bowel MALT lymphoma." (PMID 24868477, 2014). "Loss of c-IAP2 ubiquitin ligase activity, which occurs in the lymphoma-causing c-IAP2/MALT1 fusion protein, activates non-canonical NF-κB signaling and results in B cell abnormalities characteristic of MALT lymphoma." (PMID 21048983, 2010). "Thus, the c-IAP2/MALT1 fusion protein activates NF-κB by two distinct mechanisms, and loss of c-IAP2 E3 activity in vivo is sufficient to induce abnormalities common to MALT lymphoma." (PMID 21048983, 2010). "Chromosomal translocations between loci encoding MALT1 and c-IAP2 are common in MALT lymphomas." (PMID 21048983, 2010). "In addition to MCL in this study, abnormal MALT1 activity is critical for driving MALT lymphoma." (PMID 36719376, 2023). "Furthermore, frequent TNFAIP3 inactivating mutations and translocations in MALT1/IGH have been detected in H. pylori-negative gastric MALT lymphoma, suggesting that the NF-κB pathway can be a major driver in the pathogenesis of this group." (PMID 35053607, 2022). "Thus far, 8 different substrates of MALT1 have been functionally described in activated lymphocytes, and two additional substrates (NIK and LIMA1) have been reported as specific substrates of an oncogenic cIAP2-MALT1 fusion protein specifically expressed in MALT lymphoma." (PMID 30214442, 2018). "Further, MALT1-dependent cleavage of BCL10 reportedly controls integrin-dependent adhesion of T cells and MALT lymphomas." (PMID 36719376, 2023). "API2/MALT1 fusion can reduce the inhibition of API2 on apoptosis response to antigen stimulation, thus leading to MALT lymphoma of the biliary tract." (PMID 36110965, 2022). "These include chromosomal translocations involving the MALT1 or BCL10 genes, which are found in MALT lymphomas." (PMID 30214442, 2018). "The important function of MALT1 and BCL10 in antigen receptor signalling to NF-κB suggests a role for enhanced NF-κB activation in MALT lymphoma development." (PMID 19279678, 2009). "Interphase FISH showed a low frequency (7%) of FOXP1, but not MALT1 translocation in thyroid MALT lymphoma." (PMID 34021249, 2021). "Targeted sequencing confirmed that NF-κB activation is a major driver in the pathogenesis of H. pylori negative MALT lymphoma, as shown by frequent TNFAIP3 inactivating mutations and also by translocations of MALT1/IGH." (PMID 34203889, 2021). "Rearrangements in the MALT1 gene located on chromosome 18q21 and encoding MALT lymphoma translocation protein 1 are specific for MALT lymphomas; they include IGH/MALT1 translocation and API2/MALT1 fusion between the API2 (apoptosis inhibitor 2) and MALT1 genes." (PMID 34873224, 2021). "Immunophenotypically, the cells of DLBCL expressed markers of germinal center B-cells, and no MALT1 gene rearrangements, typical for MALT lymphoma, were detected." (PMID 26998372, 2016). "The API2-MALT1 fusion gene occurs by the translocation of two genes, identified as the API2 gene at 11q21 and MALT1 gene at 18q21, and translocation is particularly high at approximately 50% in pulmonary MALT lymphoma." (PMID 24371530, 2013). "In MALT lymphomas arising at gastrointestinal locations, it is claimed that MALT1, with or without bcl10 cooperation, activates the phosphorylation cascade, leading to IkB-α phosphorylation." (PMID 22472082, 2012). "While IgH/MALT1 is present in a large minority of MALT lymphomas, it occurs more commonly in non-GI sites." (PMID 21318155, 2011). "While the breakpoint on chromosome 18 is in the same region as that seen in follicular lymphoma, the gene involved is MALT1 rather than BCL2; rare cases of MALT lymphoma have reportedly been associated with the IgH-BCL2 fusion." (PMID 21318155, 2011). "The relevance of the different domains in the c-IAP2/MALT1 fusion protein to the development of MALT lymphoma has not been addressed." (PMID 21048983, 2010).
MALT lymphoma (continued). "Inhibition of MALT1 protease activity is a potential treatment approach of interest, and proof of concept data are available for several compounds; however, there are no clinical relevance yet for MALT lymphoma." (PMID 34203889, 2021). "Constitutive MALT1 protease activity and the capacity of cIAP2-MALT1 to potently activate both the canonical NF-κB1 (via the MALT1-dependent recruitment of TRAF6 and proteolytic inactivation of A20) and non-canonical NF-κB2 pathways (discussed in Section 5) drive the growth of these MALT lymphomas." (PMID 29587428, 2018). "We have found that the c-IAP2/MALT1 fusion protein activates both canonical and non-canonical signaling pathways, and activation of the latter in mice is sufficient to promote the development of features common to MALT lymphoma." (PMID 21048983, 2010). "As translocation in MALT lymphoma is mutually exclusive, additional investigations with IGH break apart probes were performed only in MALT1 negative cases, with the exception of 6 cases lacking sufficient material." (PMID 34203889, 2021). "The absence of translocations affecting the genes BCL10, MALT1, BIRC3, or FOXP1, as they are frequently seen in other types of MALT lymphomas, in six OAML analyzed by WGS is in line with published data." (PMID 32316399, 2020). "In addition to ABC DLBCL, MALT1 protease inhibition might also be beneficial for patients suffering from other lymphoid malignancies relying on constitutive CBM signaling or aberrant MALT1 protease activity, such as MCL and CLL as well as MALT lymphomas expressing the cIAP2-MALT1 fusion." (PMID 29587428, 2018).